CRP (C-reactive protein)
Diseases named in the same sentence as CRP in open-access papers (continued):
Sharing a sentence is not in itself a finding about the gene and the disease.
atherosclerosis (continued). "Previous studies reported association between CRP and atherosclerosis, and MMP12 and atherosclerotic burden." (PMID 34062730, 2021). "Thrombin-cleaved PAR1 was associated with increased plasma biomarkers such as VCAM1, ICAM-1, and E-selectin in 190 high-risk patients (CRP of mg/L 7.4 ± 6.7 mean ± SD) with chronic CVD due to atherosclerosis." (PMID 34944024, 2021). "Elevated ox-LDL levels are reported to be strongly positively linked to both atherosclerosis and inflammatory markers, including CRP, TNF-α and IL-6." (PMID 33670720, 2021). "For example, C‐reactive protein (CRP) is an established parameter to assess inflammation or the risk of coronary events in atherosclerosis." (PMID 34377374, 2021). "Elevated CRP is associated with the development of inflammation, atherosclerosis, and relevant disorders." (PMID 34135849, 2021). "Accumulating evidence has shown that CRP is pathogenic in atherosclerosis, acute myocardial infarction, cerebral infarction, and AAV disease." (PMID 33008437, 2020). "Adverse cardiovascular outcomes and prevalence of atherosclerosis have a significant association with elevated CRP levels." (PMID 33094574, 2020). "Inflammation markers, and especially CRP, are also linked to vascular stiffness, atherosclerosis and the development of end-organ damage, characteristics of a long-term hypertensive state combined with hyperlipidemia." (PMID 32933066, 2020). "There is a very strong immune component associated with AD and atherosclerosis involving similar inflammatory mediators such and CRP, TNA alpha, IL-1 and others." (PMID 33132762, 2020). "Systemic inflammation is a key determinant of accelerated atherosclerosis, while C-reactive protein (CRP), an acute-phase reactant commonly measured in practice, is associated with atherosclerosis, CV risk and mortality." (PMID 32993784, 2020). "The increase of CRP concentration occurs in chronic inflammatory situations, such as atherosclerosis, and its levels nearly triple in the presence of risk of peripheral vascular diseases." (PMID 32694929, 2020). "The studies of CRP and IMT confirmed that increased CRP is a risk factor for ischemic stroke, and atherosclerosis is measured by carotid IMT degree, i.e. the increase in IMT also increases the risk of atherosclerosis." (PMID 32214403, 2020). "In fact, interleukin-6 (IL-6) and C-reactive protein (CRP) are key inflammatory biomarkers associated with an increased risk of atherosclerosis and cardiovascular disease." (PMID 32210181, 2020). "For example, intima media thickness, a marker of preclinical atherosclerosis, was associated with increased CRP and reduced HRV in patients suffering from depression." (PMID 32230840, 2020). "This CRP property allows it, with a high sensitivity, to detect the tissue damage caused by atherosclerosis in the initial stages." (PMID 32962217, 2020). "High-sensitivity C-reactive protein (hs-CRP) levels are particularly high in symptomatic atherosclerosis, and they are associated with risk of ischemic stroke, poor outcome, and future recurrence of stroke." (PMID 33153204, 2020). "Due to the presence of CRP at atherosclerotic lesions and due to the binding capability of CRP for atherogenic LDL under certain conditions, CRP has been implicated in the development of atherosclerosis." (PMID 32849641, 2020). "Chronic low-grade inflammation, as represented by C-reactive protein (CRP), is an emerging risk factor for the development of atherosclerosis and its complications and predicts CAD and mortality independently of traditional risk factors." (PMID 31287027, 2019). "Chronic low-grade inflammation—often assessed by C-reactive protein (CRP), an acute phase reaction protein—is associated with accelerated atherosclerosis, increased CVD risk, and increased mortality." (PMID 31540528, 2019). "Atherosclerosis and cardiac disease are also associated with increased cardiovascular inflammation, specifically as measured by hs-CRP levels." (PMID 31443387, 2019).
atherosclerosis (continued). "Assessing further predictive factors among the RA-related CV risk factors, we reported an association between ACPA positivity and elevated CRP levels with subclinical atherosclerosis." (PMID 31481105, 2019). "Elevated CRP portends higher risk for MI, heart failure, atherosclerosis and mortality among RA patients." (PMID 30791646, 2019). "Several biomarkers of systemic inflammation have been associated with endothelial dysfunction and atherosclerosis, for example, IL-6 and CRP have been inversely correlated with the thickness of the intima media of the carotid in RA patients." (PMID 30818887, 2019). "Chronic inflammation has been implicated in the pathogenesis of atherosclerosis and CRP is the inflammatory biomarker that has been most consistently associated with cardiovascular disease risk." (PMID 31553765, 2019). "In contrast to CRP, there are consistent reports from multiple studies indicating a causal effect of IL-6 signaling in atherosclerosis." (PMID 31672136, 2019). "The landmark study associating systemic elevation of C-reactive protein (CRP) and the development of cardiovascular disease was the first major insight into the importance of inflammation in atherosclerosis." (PMID 31466329, 2019). "Recent studies have reported the prognostic significance of CRP/Alb ratio in patients with ST elevation myocardial infarction or stable CAD, and suggested that CRP/Alb ratio indicates higher inflammation caused by atherosclerosis." (PMID 31269058, 2019). "Blood was analysed for lipids, ESR and CRP and several biomarkers known to be associated with atherosclerosis in the general population." (PMID 31381601, 2019). "The authors concluded that CRP is a risk factor for ischemic stroke when controlling for atherosclerosis markers, such as CIMT." (PMID 31127075, 2019). "CRP-deficient mice were employed to observe any possible role of endogenous murine CRP in atherosclerosis." (PMID 31379851, 2019). "Many researchers suggest that high-sensitivity c-reactive protein (hsCRP) is a putative marker of inflammation associated with atherosclerosis at its preclinical stage, stronger, and perhaps even more objective than the classic lipid parameters." (PMID 31027378, 2019). "IL-1β has been shown to be implicated in the pathogenesis of atherosclerosis and thrombosis by the downstream stimulation of IL-6 and C-reactive protein (CRP)." (PMID 30333009, 2018). "While it is well established that CRP levels rise rapidly during acute infection, inflammation, and tissue damage, elevated CRP levels are also seen as an important risk factor for atherosclerosis, stroke, and myocardial infarction." (PMID 29668751, 2018). "Increased serum CRP levels have been associated with the development of atherosclerosis, ischemic attacks, hemorrhagic stroke, as well as disease outcomes." (PMID 29189992, 2018). "Increased levels of 3NT were associated with atherosclerosis and observed in patients with coronary dysfunction, as well as after the removal of the cardiovascular risk factors and normalization of C reactive protein." (PMID 30050649, 2018). "Inflammation plays a key role in setting the stage leading to atherosclerosis progression, and high-sensitivity C-reactive protein (CRP) has been recognized as a predictor of cardiovascular risk." (PMID 29644527, 2018). "Of note, the uric acid level was also associated with the high-sensitivity C-reactive protein level and cIMT, markers of systemic inflammation and preclinical atherosclerosis." (PMID 29588485, 2018). "The autodestructive association of CRP and AP with activated complement fragments attached to host tissue has been seen in degenerative conditions, such as atherosclerosis and AD." (PMID 30555318, 2018). "The association initially seemed potentially consistent with a pathogenic role for CRP in atherosclerosis and stimulated very widespread clinical interest in CRP, particularly as it was so easy to measure." (PMID 30459761, 2018).
atherosclerosis (continued). "The decrease of CRP after treatment is an evidence of decreased systemic low-grade inflammation implicated in atherosclerosis." (PMID 28947858, 2017). "Other studies have also reported an association between CRP and atherosclerosis, as well as future cardiovascular events in RA." (PMID 28400572, 2017). "Elevated plasma levels of CRP are independently associated with increased risk of atherosclerosis, thus hs-CRP is probably one of the most promising biomarkers of vascular inflammation in high-risk patients." (PMID 28125968, 2017). "Of note, some pro-inflammatory proteins, including CRP and serum amyloid A-1 protein, act on endothelial cells resulting in acute effects of thrombosis and chronic effects of atherosclerosis, subsequently increasing the risk of stroke." (PMID 29245986, 2017). "Increased hepatic production of CRP and fibrinogen has been identified as a key element of MS, associated with the pathogenesis of atherosclerosis." (PMID 29321950, 2017). "In contrast, data from the Mendelian randomization genetic studies suggested that the CRP more likely is an innocent bystander than a cause of atherosclerosis." (PMID 28676043, 2017). "For example, the consumption of polyphenols, flavonoids and antioxidants has been linked to improvements in blood pressure, endothelial function and reductions in pro-inflammatory markers associated with atherosclerosis, such as C-reactive protein (CRP)." (PMID 28212320, 2017). "CRP is used to predict atherosclerosis risk and it has shown in larger clinical trial to be a strong predictor of CVD risk." (PMID 27846846, 2016). "Acting as an inflammation marker and involved in the pathogenesis of atherosclerosis, CRP has been identified as cardiovascular risk factors." (PMID 27434049, 2016). "CRP, a stable downstream marker of the inflammatory process, has been reported to be an independent predictor of the risk of atherosclerosis, cardiovascular events, and myocardial infarction." (PMID 27616738, 2016). "Association between elevated C-reactive protein (CRP) serum levels and subclinical atherosclerosis and cardiovascular (CV) events was described in rheumatoid arthritis (RA)." (PMID 27534721, 2016). "There is growing evidence that hs-CRP is an important marker of cardiovascular risk and is linked to the pathophysiology of atherosclerosis, providing additional value in primary and secondary prevention." (PMID 28190984, 2016). "It has been suggested that the relationship between increased serum CRP levels and stroke risk is because of the inflammation seen in atherosclerosis." (PMID 27355961, 2016). "At each time point, they were monitored for inflammatory markers (high sensitivity C Reactive Protein {hsCRP} and fibrinogen), cardiovascular risk factors and atherosclerosis burden." (PMID 25888123, 2015). "Serum biomarkers such as CRP, homocysteine and matrix metalloproteinases suggest underlying inflammation, atherosclerosis and deranged extracellular matrix metabolism as possible pathogenic mechanisms." (PMID 26239448, 2015). "CRP is an acute-phase reactant marker for underlying systemic inflammation and a strong predictor for atherosclerosis, coronary artery disease, and myocardial infarction." (PMID 25616223, 2015). "Serum cytokines and C-reactive protein (CRP) are known as one of the major risk factors in atherosclerosis." (PMID 26080030, 2015). "Considering the existing similarities between atherosclerosis and AS, we examined the effect of CRP rs1205 C>T polymorphism on the AS severity." (PMID 26473826, 2015). "Last but not least, TNF antagonists improve biomarkers of inflammation such as C-reactive protein, which are independent risk factors of atherosclerosis." (PMID 26633680, 2015). "CRP reflecting systemic inflammation, was a well-established marker of atherosclerosis and one of the classical biomarkers for increasing risk of PAD." (PMID 25850006, 2015).
atherosclerosis (continued). "Several studies have linked cigarette smoking to the presence and progression of atherosclerosis, and to markers of systemic inflammation including high-sensitivity C - Reactive Protein (hs-CRP)." (PMID 25960769, 2014). "Hs-CRP/APN ratio was a useful predictor to discriminate subjects who were at increased risk of atherosclerosis progression." (PMID 25070472, 2014). "Based on the identification of CRP as a cardiovascular risk marker in humans, the vast amount of experimental research with human material has been performed on atherosclerosis as the underlying cause for many cardiovascular disease entities." (PMID 24799767, 2014). "Possible links between CRP and adhesion molecule expression and between CRP and atherosclerosis have been reported, and an association has been demonstrated between elevated CRP levels and development of CAV and graft failure in heart transplant recipients." (PMID 25490200, 2014). "PTX3 in humans, like CRP, correlates with surrogate markers of atherosclerosis and is independently associated with the risk of developing vascular events." (PMID 23690668, 2013). "Because inflammation plays a pivotal role in the pathogenesis of both MS and atherosclerosis, we investigated the association between CRP and MDA-LDL levels." (PMID 24314067, 2013). "An elevated CRP level, which is a marker of malnutrition, inflammation, and atherosclerosis (the MIA syndrome), is a risk factor for morbidity and mortality in the general population and in dialysis patients." (PMID 24007461, 2013). "Fourth, chronic infectious burden and elevated inflammatory markers, such as C-reactive protein and interleukin-6, have been associated with the development of atherosclerosis and increased risk of stroke." (PMID 24023710, 2013). "Adipocytokines such as interleukin-6 (IL-6) and adiponectin as well as inflammatory cytokines such as C-reactive protein (CRP) are associated with the development of atherosclerosis and type 2 diabetes in adults." (PMID 23984329, 2013). "Previous studies have demonstrated that circulating CRP is an independent risk factor for type 2 diabetes and atherosclerosis." (PMID 22292925, 2012). "Several studies have reported a positive association between CRP levels and cardiovascular events and atherosclerosis." (PMID 22505888, 2012). "The association between CRP and early atherosclerosis is documented by numerous works and CRP is recently proposed as cause of the latter." (PMID 22424154, 2012). "Various studies have reported contradicting results on association between CRP levels and severity and progression of atherosclerosis." (PMID 22505888, 2012). "In CKD patients, it has been reported that CRP is closely associated with the severity of atherosclerosis and cardiovascular events." (PMID 22583484, 2012). "IL-6 also stimulates the synthesis of CRP, which is well known as both a marker and important risk factor of atherosclerosis in the general population and CKD patients." (PMID 22567283, 2012). "Collectively, these findings support the suggestion that intracellular ROS generation is associated with CRP-associated atherosclerosis." (PMID 23162475, 2012). "High-sensitivity C-reactive protein (hs-CRP) has emerged as a useful marker for inflammation associated with atherosclerosis and cardiovascular disease." (PMID 29062730, 2012). "The causal role of CRP in the pathophysiology of atherosclerosis is currently an area of great controversy." (PMID 21219634, 2011). "When comparing dietary SFC, UF and S, dietary SFC induces CRP-associated early atherosclerosis and ectopic fat deposition whereas isoenergetic UF shows beneficial effects on postprandial glycaemia, inflammation and body composition in diabetic pigs." (PMID 21756316, 2011). "C-reactive protein (CRP) is an acute-phase reactant and a marker for underlying systemic inflammation, including atherosclerosis and plaque rupture with ensuing thrombus formation." (PMID 21958326, 2011).
atherosclerosis (continued). "The pro-inflammatory cytokines TNF-α, IL-1β, IL-6, and other acute phase proteins such as serum amyloid A (SAA) and C-reactive protein (CRP) have been associated with atherosclerosis or increased risk of cardiovascular disease." (PMID 21249123, 2011). "Examples are the recently published evidence for the causal role of body mass index on blood pressure or accumulating evidence against the causal role of CRP in coronary heart disease or atherosclerosis." (PMID 20616999, 2010). "Further, lipoxygenase pathway SNPs that were associated with measures of atherosclerosis were associated with markers of inflammation (CRP, ICAM-1) and calcification (MGP).Conclusions." (PMID 20592751, 2010). "C-reactive protein (CRP) has been recommended as the marker of choice to monitor cardiovascular risk, being a stronger predictor of atherosclerosis than even plasma low density lipoprotein (LDL) concentration." (PMID 19804641, 2009). "Animal studies also support the proinflammatory and pro-atherogenic role of CRP, because administration of human CRP or over-expression of CRP in apolipoprotein E -deficient mice promotes the development of spontaneous atherosclerosis." (PMID 19240794, 2009). "Several studies have shown that elevated plasma levels of C-reactive protein (CRP), interleukin-6 (IL-6), fibrinogen and other soluble inflammatory mediators are associated with both the severity of atherosclerosis and the risk of CHD." (PMID 19639050, 2009). "In conclusion, plasma levels of CRP are associated not only with the presence of atherosclerosis but also with its clinical severity in the target population of this study." (PMID 20508761, 2008). "Plasma levels of CRP are associated with not only the presence of atherosclerosis but also with its chronological clinical severity." (PMID 20508761, 2008). "The inflammatory marker CRP has been found to be associated with the presence of atherosclerosis and to double the risk of future cardiovascular events when exceeding 3 mg/L." (PMID 18518944, 2008). "Recent evidences have suggested a possible direct pathogenic role for CRP in atherosclerosis process and plaque formation and increasing of CRP level promote arterial atherosclerosis." (PMID 18513415, 2008). "C-reactive protein (CRP), a marker of systemic inflammation, is associated with risk of coronary events and sub-clinical measures of atherosclerosis." (PMID 18714381, 2008). "Evidence in support of this link being causal would include an association robust to adjustments for confounders (multivariable standard regression analysis) and the association of CRP gene polymorphisms with atherosclerosis (Mendelian randomization analysis)." (PMID 18714381, 2008). "Previous studies have shown that CRP, aproduct of the inflammatory response, contributes to atherosclerosis,cardiovascular risk, and mortality in dialysis patients." (PMID 18288267, 2007). "Several CVdisorders, including atherosclerosis, are associated withendothelial dysfunction, as well as enhanced expression of CRP and ET-1." (PMID 17497038, 2007). "We further show here that CRP is a major risk factor for atherosclerosis in patients first presenting with RA." (PMID 17986352, 2007). "C-reactive protein in particular is also increasingly being implicated in the pathogenesis of atherosclerosis." (PMID 15974805, 2005). "Many studies also suggest that smoking induces inflammatory factors (TNF-α, CRP, IL-6, fibrinogen, etc.)that are risk factors for atherosclerosis and cardiovascular diseases." (PMID 16262911, 2005). "Additionally, the presence of high levels of inflammatory markers such as elevated levels of CRP and interleukin-6 (IL-6), has been linked to the progression of atherosclerosis in NCVs." (PMID 41517773, 2026). "Moreover, inflammatory markers associated with atherosclerosis, such as C-reactive protein (CRP), IL-6, TNF-α, leptin, and adiponectin, are elevated at younger ages in women with PCOS, particularly in those who are obese." (PMID 40149685, 2025).